SMAD7 (SMAD family member 7)
Diseases named in the same sentence as SMAD7 in open-access papers (continued):
Sharing a sentence is not in itself a finding about the gene and the disease.
tumor (continued). "Asiatic acid (AA) is a triterpenoid component isolated from Centella asiatica, functions as a Smad7 agonist shows pharmacological effects on anti‐inflammation, antioxidation, anti‐tumour, neuroprotection, hepatoprotection and wound healing." (PMID 34514726, 2021). "The expression of Smad7 in T cells led to an increase in the number of tumor-infiltrating T-bet/RORγ-t double-positive CD4+ T cells while decreasing the expression of IL-17A in CD+ T cells." (PMID 34059951, 2021). "In line with our notion, we detected a hyperactivation of Smad3 but inhibition of Smad7 in the primary HCC compared to the paired non‐tumour liver tissue." (PMID 34514726, 2021). "The genes SMAD7, TGFBR2 and TNFAIP3 were associated with both tumour suppressor and oncogenic roles." (PMID 34198662, 2021). "In PANC-1 cells, PLEXIND1 downregulation results in a decrease in protein expression of the SMAD3 and mRNA levels of SMAD7 and Serpine1, potentially abetting tumor suppression." (PMID 34439202, 2021). "Blocking TGF-β activity in OS cells by SMAD7 overexpression has decreased primary tumor growth by affecting the relationships between tumor cells and non-tumor cells." (PMID 32326444, 2020). "It seems that REGγ impinges on repression of thyroid-specific genes and promotion of tumor malignancy in ATC cells by activating the TGF-β signal pathway via degradation of Smad7." (PMID 31243343, 2020). "In summary, lncRNA DGCR5 acts as a tumor suppressor through the DGCR5/miR-21/Smad7 and DGCR5/miR-23a/PTEN axes." (PMID 33085646, 2020). "1D11 treatment significantly inhibited the level of TGF-β and SMAD7 in SW480 cells when tumor cells were co-cultured with TANs (P<0.05)." (PMID 32201528, 2020). "By comprehensively analyzing the microRNAs′ potential target genes and tumor pathways′ core genes, together with the conservation and mirSVR score of miRNAs and its targets, we ultimately identified miR-581 and SMAD7 of TGF-beta signal pathways." (PMID 32899503, 2020). "Many studies have shown that TGF-β can serve as a tumour suppressors to induce the expression of Smad7 and p21(CDKN1A) in certain cancers." (PMID 31728016, 2020). "According to the image created by UCSC Xena, in the TCGA tumor samples, the DNA copy numbers of Siglec-15, SMAD7 and ATP5A1 showed a similar trend, while Siglec-15 and CD274 (PD-L1) showed the opposite trend." (PMID 32201516, 2020). "It has been suggested that SMAD7 can switch from tumor-suppressive to tumor-promoting depending on the tumor stage." (PMID 32190221, 2020). "Another study showed that miR-181c was downregulated in metastatic NB tissues compared with primary NB tissues and that acted as tumor suppressor by reducing SMAD7 expression." (PMID 32337068, 2020). "LncRNA DGCR5 exerted its tumor-suppressive effects through the DGCR5/miR-21/Smad7 and DGCR5/miR-23a/PTEN axes." (PMID 33085646, 2020). "We have previously shown that Smad7 is up-regulated in several human CRC cell lines as well as in human sporadic CRC tissue as compared to non-tumor tissue." (PMID 31052449, 2019). "For instance, it is still unclear how Smad7 exactly regulates CRC cell growth and death and if the regulatory effect of Smad7 can be influenced by the histologic type and stage of the neoplasia." (PMID 31052449, 2019). "The incidence rate in forming tumor spheres is higher in SMAD7-silenced NPC cells than control cells." (PMID 31681406, 2019). "SMAD7 has a tumor suppressing role through blocking the TGF-β-stimulated cancer progression by increasing angiogenesis and inducing EMT." (PMID 31540229, 2019). "The tumor spheres consisted of SMAD7-silenced NPC cells were also larger in volume compared to control cells." (PMID 31681406, 2019). "Smad7 over-expression in T cells promotes infiltration of the tumor environment by Tbet/RAR-related orphan receptor (ROR)-γt double-positive CD4 T cells, which produce high levels of tumor necrosis factor (TNF)-α and IFN-γ, but lower levels of IL-17A." (PMID 31052449, 2019).
tumor (continued). "Next, we explored the biological role of SMAD7 in vivo; the tumor volume was reduced in SMAD7-Flag overexpression group compared to that in the control group (expressing GFP tag) in the xenograft mouse model." (PMID 31711043, 2019). "Tumor spheres analyses were used to further examine the stemness phenotypes of NPC cells which were transfected with SMAD7 expression plasmids." (PMID 31681406, 2019). "By the staining of sporadic CRC sections, we also showed that cancer cells are the major producers of Smad7 within the tumor microenvironment." (PMID 31052449, 2019). "The data showed that CNE2-BART7-3p or 5-8F-BART7-3p cells which were transfected with SMAD7 plasmids had lower efficiency in forming tumor spheres than their counterparts which were transfected with control vectors." (PMID 31681406, 2019). "Collectively, it appears that tumor cell type dictates SMAD7 function as a tumor promoter or suppressor." (PMID 29799477, 2018). "In this study, our experimental results indicated that GC-derived exosomal miR-21-5p can convert PMCs into MMT via targeting SMAD7, leading to the increased invasion of PMCs and attachment to tumor cells." (PMID 30154401, 2018). "Even in the same tumor, the function of Smad7 can switch from tumor suppressive to tumor promoting depending on the tumor stage (i.e., early versus advanced)." (PMID 30498395, 2018). "There is a controversy regarding the role of Smad7 in tumor development depending on the type of the tumor." (PMID 30498395, 2018). "Consistently and in line with a previous report showing that SMAD7 inhibits mouse tumorigenesis by inhibiting NF-κB signaling, we found upregulation of pIκBα in SMAD7 overexpressing mouse tumor tissue." (PMID 28134936, 2017). "Building on these results, we found for the first time a link between induced STAT3 signaling and hepatocyte-specific SMAD7 deficiency in DEN mice and human HCC, thus unraveling a new tumor-suppressive mechanism for SMAD7 in HCC." (PMID 28134936, 2017). "The high risk of tumor recurrence and metastasis suggests that CRC patients with high miR-4775 expression and Smad7/TGFβ pathway activation should receive individualized and more aggressive treatment after tumor resection." (PMID 28095858, 2017). "Downregulating miR-4775 or overexpressing Smad7 reversed the tumor-promoting roles of miR-4775/Smad7/TGFβ in vitro and in vivo." (PMID 28095858, 2017). "In line with our findings in patients, Smad7 levels in both tumor tissue as well as surrounding tissue show a significant inverse correlation with tumor numbers." (PMID 28134936, 2017). "To further delineate the pathways affected by SMAD7 mediating its tumor-suppressive function, we next analyzed the components described to interact with SMAD7/TGF-β signaling or impact HCC development using the same tissue samples as above." (PMID 28134936, 2017). "Although many details of the mechanistic integration and crosstalk of this new pathway with the canonical SMAD7/TGF-β signaling and its functional switch in CLD progression remain open, it strengthens the tumor-suppressive role of SMAD7 in late-stage disease." (PMID 28134936, 2017). "Smad7 levels in tumors as well as in the surrounding tissue were negatively correlated with tumor numbers (P=0.0449 and P=0.0037, respectively)." (PMID 28134936, 2017). "In order to understand the molecular mechanism of SMAD7 as a tumor suppressor in the development of HCC, Tamoxifen-inducible hepatocyte-specific SMAD7 expression was induced or blunted using albumin promoter-driven constructs in SMAD7 Tg and SMAD7 KO mice." (PMID 28134936, 2017). "Together, our results provide new mechanistic insights into the tumor-suppressive functions of SMAD7 in hepatocarcinogenesis." (PMID 28134936, 2017).
tumor (continued). "Studies have indicated that overexpression of Smad7 impaired the metastasis and invasion of tumor cells via negative regulation of TGF-β." (PMID 27006642, 2016). "Concordant to the difference in bone damages, there were significantly more osteoclasts along the tumour–bone interface when the tumour cells overexpressed miR-182, and this increment was suppressed by SMAD7 overexpression." (PMID 27996004, 2016). "Collectively, our data support the conclusion that miR-182 targets SMAD7 to enhance TGFβ signalling in cancer cell lines and human tumour samples." (PMID 27996004, 2016). "The augmented invasiveness was accompanied by attenuated SMAD7 and enhanced Vimentin both at the edge and the interior areas of the tumours, as revealed by immunohistochemistry (IHC) analyses." (PMID 27996004, 2016). "With respect to the role of Smad7 in tumorigenesis, because TGFβ is a potent growth inhibitor and apoptosis inducer, the anti-TGFβ effect of Smad7 is suspected to promote tumor growth and survival." (PMID 25566830, 2015). "We can recognize several further microRNAs positively correlated with TGFβ role as a supporter of tumor growth: miR-21, shown to be induced by TGFβ1 and to target SMAD7, thus leading to the TGFβ-promoted formation of cancer associated fibroblasts." (PMID 26188123, 2015). "Smad7 overexpressing T cells further exhibited direct killing of tumor cells via TNF-α, thus demonstrating an additional mechanism accounting for Th17/Th1 hybrid cell antitumor functions." (PMID 26583099, 2015). "Specifically, in panels D, a Gli1 molecule and a GLI2 molecule had weak expressions; the expressions of E-cadherin and SMAD-7 were significantly increased in the tumor areas, and the differences were statistically significant." (PMID 25895132, 2015). "The observed increased anti-tumor response seems to be in part the result of TGF-β insensitivity due to SMAD7 degradation after Cbl-b ubiquitination." (PMID 25815272, 2015). "Functional studies reported that over expression of miR-216a can activates the PI3K/Akt and TGF-β pathways by targeting PTEN and SMAD7, contributing to hepato carcinogenesis and tumor recurrence in hepatic cell cancer." (PMID 26402912, 2015). "This is mainly because Smad7 overexpression in tumor cells affects the “vicious cycle” established between tumor cells and bone cells by its ability to decrease osteoclast activity." (PMID 26015407, 2015). "It is known that EMT is a process associated with many factors, of which TGF-β, Vimentin, ZEB-1, SMAD-7, E-cadherin and N-cadherin molecules are closely associated with the typical phenotype change of EMT in the process of tumor cell growth." (PMID 24625224, 2014). "Consistent with the western blot results, the expression of TGF-β, Vimentin, ZEB-1 and N-cadherin detected by immunohistochemistry assay was also remarkably decreased, whereas the expression of SMAD-7 and E-cadherin was notably increased in the tumor tissues." (PMID 24625224, 2014). "In contrast, two studies by Mauviel’s group reported a TGF-β-dependent tumor-suppressive role of Smad7 in metastatic melanoma cells." (PMID 24317436, 2013). "Investigating the intracellular signalling events leading to CCN2 and type I collagen down-regulation, we found that tumour cell-mediated up-regulation of Smad7 negatively affected the MEK/ERK pathway." (PMID 24090133, 2013). "Mechanistically, it was proposed that Smad7 promoted heterotypic cell-cell interactions through the redistribution of cell adhesion proteins to the cell surface thereby mitigating tumor invasion." (PMID 24317436, 2013). "TGF-β1 mRNA levels were higher in tumor than in peritumor, which positively correlated with Smad2 and Smad7." (PMID 23342108, 2013). "The data described in this article indicate that Smad7 can have both pro- and anti-tumor actions depending on the cancer type analyzed." (PMID 24317436, 2013).
tumor (continued). "ERK signalling was also shown to be impaired in CCD-1068SK fibroblasts after direct co-culture with MDA-MB-231 tumour cells, with Smad7 overexpression in fibroblasts leading to a similar decrease in ERK activity." (PMID 24090133, 2013). "The second study, conducted on patient samples, contradicts this and demonstrates that the increased expressions of either Smad6 or Smad7 are infrequent in tumor compared to normal samples." (PMID 22195733, 2011). "IL10, PTGS2, and FASL are known to suppress the immune response and SMAD7 which inhibit TGFβ, and bone morphogenetic protein expression was downregulated which would lead to an environment favoring tumor growth." (PMID 22013484, 2011). "We then showed that overexpression of SMAD7 in a highly invasive and metastatic cell line, 1205Lu, inhibits subcutaneous tumor growth as well as incidence and size of osteolytic bone metastases in mice, accompanied with dramatically increased survival." (PMID 21211030, 2011). "The difference in the expression levels of Smad7 in normal pancreatic samples as compared to tumor samples was highly significant by Fisher's exact test (p = 0.0005)." (PMID 22195733, 2011). "Overexpression of Smad7 in breast cancer cells led to reduction in metastasis and improvement of survival in tumor-bearing mice." (PMID 22204639, 2011). "An increased expression of mouse-derived cytokines IFNG and interleukin 7 was found in VEGFA165 tumours, both described to induce SMAD7 expression." (PMID 22045186, 2011). "The cytoplasmic staining of Smad6 and Smad7 in most samples implies that these two inhibitory Smads were in their activated states in most tumor samples." (PMID 22195733, 2011). "There was a significant difference in protein expressions of Smad4 (p = 0.0001), Smad6 (p = 0.0015) and Smad7 (p = 0.0005) protein in tumor as compared to paired normal samples." (PMID 22195733, 2011). "Collectively, these studies indicate that Smad7 has a tumor-promoting function, most likely due to its inhibitory effect on the tumor suppressor activity of TGF-β." (PMID 22204639, 2011). "Our study goes a step further, and shows that Smad6 as well as Smad7 are lost in tumor as compared to normal samples." (PMID 22195733, 2011). "Diurnal expressions of Smad3 and Smad7 mRNA were observed in tumor‐infiltrated CD8+ T cells." (PMID 41257391, 2026). "It was shown that TGF-β acting through SMAD4 and SMAD7 transduction enhances the recruitment of monocytes and activation of macrophages, suppresses the functioning of anti-tumor T-cells and generates immunosuppressive TIME facilitating immune evasion mechanisms and tumor progression." (PMID 39936166, 2025). "Our results revealed that sja-let-7 mimics led to a significant downregulation of TGF-β, TGF-βR1, and SMAD2, while the antagonist SMAD7 was upregulated, suggesting that the anti-tumor effects of sja-let-7 may involve modulation of the TGF-β/SMAD pathway." (PMID 39336756, 2024). "Similarly, ALKBH1 overexpression promotes metastasis in CRC through modifying METTL3 mRNA m1A levels, resulting in reduced protein translation, increased m6A demethylation of SMAD7 mRNA, and enhanced tumor migration and invasion." (PMID 38317214, 2024). "The tumor suppressive role of SMAD7 was further validated in A549 and HCC827 LAD cell lines." (PMID 37072414, 2023). "High SMAD7 expression was positively correlated with several features of tumour aggressiveness such as the presence of ulceration (p < 0.001), higher tumour thickness (p < 0.001), and mitotic rate (p < 0.001), but not the presence of regional or distant metastases." (PMID 37685308, 2023). "Moreover, our data revealed that PHF14 expression correlates with lowered SMAD7 level and shorter survival of LAD patients, and importantly that SMAD7 methylation level of circulating tumor DNA (ctDNA) can potentially be used for prognosis prediction." (PMID 37072414, 2023). "Previous studies have shown that SMAD7 was a tumor suppressor in a variety of cancers." (PMID 36550779, 2023).
tumor (continued). "In addition, JPHYD significantly inhibited the expression of miR21-5p and the protein levels of Smad3, Vimentin, Snail, and N-cadherin, while E-cadherin and Smad7 proteins increased in tumor tissues treated with JPHYD." (PMID 35518787, 2022). "Interestingly, the study also suggests that hypoxic conditions render Smad7 a tumor promoter, even though it is a tumor suppressor under normoxic conditions." (PMID 35625561, 2022). "SMAD7, HIF-1α gene, and HIF-1α protein may be jointly implicated in cancer development and prognosis, while SEC13, GHRL, and lncRNA GHRLOS may act as tumor suppressors." (PMID 35449150, 2022). "Collectively, our data revealed that circFGGY inhibits the proliferation and invasion of HCC cells by sponging miR-545-3p and promote the expression of Smad7, indicating that circFGGY functions as a tumor suppressor and could be a prognostic biomarker for HCC." (PMID 35592246, 2022). "Nevertheless, several studies have pointed out that SMAD7 might promote tumor progression, migration, and invasion." (PMID 35912252, 2022). "Finally, SETDB1 silencing in BC cells inhibited tumor metastasis through regulation of Mothers against decapentaplegic homolog 7 (SMAD7) expression, which antagonized the transforming growth factor beta (TGF-β) pathway." (PMID 34440561, 2021). "Thus, Smad7 can be used as a marker of aggressive tumor behavior and adverse clinical in patients with melanoma." (PMID 34059951, 2021). "Deletion of Smad7 can enhance tumor sensitivity and inhibit TGF-β activity." (PMID 34059951, 2021). "In addition, the study suggested that SMAD7 and SNAI1 hypomethylation is associated with tumor recurrence." (PMID 34571856, 2021). "SMAD2 knockdown effectively increases this effect of SMAD3/4, and inducing the transcription of SMAD7 may prevent TGF-β-induced EMT of tumor cells; thus, SAMD7 and SAMD2 may play a role in EMT to regulate tumor metastasis." (PMID 34367975, 2021). "In another research, researchers discovered a decrease in circ-SMAD7 in ESCC patients’ plasma could block tumor proliferation and migration." (PMID 33292234, 2020). "Smad7 has also been confirmed to be a downstream target of miRNA-192, and their interaction could promote epithelial-to-mesangial transition in tumor cells." (PMID 32215042, 2020). "Functional investigations showed that SNAI3-AS1 may affect tumorigenesis by inducing tumor epithelial to mesenchymal transition via regulating the UPF1/Smad7 signaling pathway." (PMID 32802843, 2020). "We report here that Smad7, a classical TGF-β target gene so far recognized mainly as a negative regulator of TGF-β signaling, also can act in the nucleus as a positive regulator of transcription of two tumor-promoting genes, which are linked to tumor invasion." (PMID 32888405, 2020). "However, recent studies have revealed new mechanistic insights into the tumor-suppressive functions of SMAD7 in hepatocarcinogenesis and subsequent tumor progression." (PMID 31711043, 2019). "In the line of the changing nature of TGFβ pathway during tumour progression, it has been pointed that Smad7, a TGFβ pathway component, can be considered as a “swith” acting as an inhibitor of TGFβ pathway in early stages of tumour progression and as a enhancer of tumour invasion in late stages." (PMID 31388092, 2019). "Next, we intended to determine whether the anti-tumor activity of Tan IIA exerted by up-regulating SMAD7 is dependent on YAP." (PMID 31711043, 2019). "Additionally, qPCR and IHC staining in subcutaneous tumour xenografts and intraperitoneal nodules showed reduced Smad7 levels in miR-520h-overexpressing tumours, and the opposite results in miR-520-silenced tumours." (PMID 30158641, 2018). "The data also indicated that exosomal miR-21-5p transferred from GC cells could induce MMT in MCs via targeting SMAD7 and reduce tumor peritoneal metastasis." (PMID 30154401, 2018).